MAVS (mitochondrial antiviral signaling protein)
Diseases named in the same sentence as MAVS in open-access papers (continued):
Sharing a sentence is not in itself a finding about the gene and the disease.
viral infection (continued). "Caspase-3 cleaves MAVS at D429/490 during virus infection and cell apoptosis; a series of MAVS mutants were constructed in which potential D residues were replaced with A residues." (PMID 35782136, 2022). "The signaling adaptor MAVS forms prion-like aggregates to activate the innate antiviral immune response after viral infection." (PMID 36028484, 2022). "Their findings elucidated that the RNF34‐mediated autophagic degradation of MAVS links to the innate immune response, mitochondrial homeostasis, and viral infection." (PMID 36042206, 2022). "We also found that knockdown of PB1 slowed the degradation of endogenous MAVS after SZ19 virus infection." (PMID 33577621, 2021). "The interacting components then activate MAVS and TNF receptor-associated factors (TRAF)-mediated downstream signaling during virus infection." (PMID 34707613, 2021). "The mitochondrial location of NLRP3 is also affected by the interaction between MFN2 and MAVS during viral infections, which recruits the inflammasome to the MAMs." (PMID 33796100, 2021). "Based on these findings, we suggest that HHV-6 U26 targets MAVS signaling to evade viral infection in host cells." (PMID 33593967, 2021). "Upon viral infection, RIG-I detects viral RNA and catalyzes the self-association of MAVS on the mitochondrial membrane and subsequent conversion into very large prion-like aggregates that potently activate IRF3." (PMID 34578357, 2021). "Together, these data suggest that MFN1 and MFN2 interact with MAVS to fine-tune innate immune responses during viral infection." (PMID 34482801, 2021). "In the further study, we used indirect immunofluorescence and virus titer assay to confirm that the reduction in MAVS was related to virus infection in Vero cells." (PMID 34696420, 2021). "The deletion of MAVS has been shown to significantly reduce the levels of antiviral and other pro-inflammatory cytokines normally induced by virus infection." (PMID 33807534, 2021). "Many reports have focused on the interaction and regulated mechanisms between virus infection and MAVS function." (PMID 34696420, 2021). "During the late stage of viral infection, MAVS function is negatively regulated by UBX-domain-containing protein 1 (UBXN1)." (PMID 34782737, 2021). "After viral infection, E3 ubiquitin ligase MARCH8 is recruited by antiviral factor Tetherin (BST2/CD317) and mediates K27-linked ubiquitination of MAVS at K7." (PMID 34566944, 2021). "As expected, overexpression of USP18 caused the formation of more MAVS aggregates, while the deletion of USP18 negatively regulated the aggregation of MAVS upon viral infection." (PMID 34016972, 2021). "Upon viral infection, TRIM31 is recruited to MAVS and catalyze the K63-linked polyubiquitination at K10, K311, and K461, leading to the higher efficient formation of MAVS prion-like aggregates." (PMID 34566944, 2021). "Previous work has shown that signaling output from MAVS located to distinct subcellular compartments correlates with the ability to control viral infection." (PMID 34108265, 2021). "For instance, TRIM31 promotes the K63-linked polyubiquitination of mitochondrial antiviral signaling protein (MAVS) by inducing expression of interferons (IFNs) to against viral infection." (PMID 34124071, 2021). "The HECT domain E3 ligaseITCH, which is recruited to the mitochondria in response to viral infection, was identified as a negative regulator of RLR-signaling, inducing MAVS degradation by ubiquitination with K48-linked ubiquitin chains at K371 and K420." (PMID 33808506, 2021). "TRIM31 was previously reported to translocate to mitochondria to interact with MAVS following viral infection." (PMID 34016972, 2021). "In epithelial-like HEK293T and HeLa cells, NLRX1 acts as a negative regulator of RLR-mediated antiviral signaling, as it decreases type I IFN production following viral infection via interacting with the adaptor protein MAVS and inhibiting IRF3 dimerization." (PMID 33525671, 2021).
viral infection (continued). "Next, both co-immunoprecipitation assays and confocal microscopy indicated RNF90 interacted with MAVS, and this interaction was enhanced by viral infection." (PMID 34512666, 2021). "This further supports the notion that Tom70’s role in activating MAVS protein that promotes apoptosis during viral infection, which is probably altered by SARS-CoV-2 infection." (PMID 34841263, 2021). "RIG-I plays a key role in recognizing viral infection, and its activated conformer engages the adaptor mitochondrial antiviral signaling protein (MAVS) to mediate the activation of transcription factors and interferon-stimulated gene (ISG)." (PMID 34307373, 2021). "We sought to determine the mechanism underlying the recruitment of the ER-to-Golgi resident TRAF3 to membrane-bound MAVS for the formation of functional signalling complex upon viral infection." (PMID 33411856, 2021). "The data from our IFA analysis suggested that, with the extension of virus infection time, the number of cells expressing aMPV/C N protein showed an increasing trend, while expression of MAVS decreased gradually." (PMID 34696420, 2021). "siRNA knockdown of METTL14 expression in primary peritoneal macrophages also elevated MAVS protein level after virus infection." (PMID 34047074, 2021). "In response to viral infection, TRIM25 has previously been reported to mediate the K48-linked ubiquitination of MAVS causing its proteasomal degradation to negatively regulate IFN-β production, and the K63-linked ubiquitination of the RIG-I receptor." (PMID 34445801, 2021). "Some research groups found no changes, whereas others published a negative regulatory role of NLRX1 in MAVS-dependent type I IFN production of MEFs as a response to viral infection." (PMID 33525671, 2021). "These proteins act as sensors of viral infection and through the activation of proteins such as MAVS, mediate the induction of type I IFN pathway." (PMID 33984068, 2021). "The interaction between USP18 and MAVS is enhanced following viral infection, suggesting the possible regulation of MAVS activity by USP18." (PMID 34016972, 2021). "Upon virus infection, MAVS forms prion-like aggregates on the mitochondria and acts as a scaffold to recruit downstream/upstream proteins, leading to the production of IFNs." (PMID 33600488, 2021). "Although this was described using a model of viral infection, MAVS is increasingly showing to interact with many important enzymes beyond its role as an adaptor for cytosolic PRRs RIG-I and MDA-5." (PMID 33796100, 2021). "Upon viral infection, MAVS forms prion-like aggregates by receiving the cytosolic RNA sensor retinoic acid-inducible gene I-activated signaling and further activates/switches on the type I interferon signaling." (PMID 34566944, 2021). "A previous report showed that TOMM70 acts as receptor of the MT antiviral-signaling protein (MAVS) and thereby participates in the corresponding system of innate immunity against viral infections." (PMID 34368262, 2021). "Upon viral infection, peroxisomal MAVS provides short-term protection by rapidly inducing IFN-independent expression factors, whereas mitochondrial MAVS has been associated with the activation of a more stable antiviral response involving IFN production." (PMID 33807534, 2021). "As we revealed that both virus infection and poly I:C has similar effect on MAVS, dsRNA other than virus proteins are indicated to be involved in this process." (PMID 32943610, 2020). "Eventually, TOM70 was found to provide the essential receptor structure for the mitochondrial antiviral-signaling protein MAVS, a major sensor of viral infections in the innate immune system." (PMID 33019591, 2020). "TOM70 acts as receptor of the mitochondrial antiviral-signaling protein (MAVS) and thereby participates in the corresponding system of innate immunity against viral infections." (PMID 33019591, 2020).
viral infection (continued). "For example, viral infection induces the expression of the E3 ligase TRIM21, which binds MAVS to promote its K27-linked polyubiquitination at lysine 325 and its association with TBK1." (PMID 32117959, 2020). "One study suggested that mitochondria play important roles in the innate immune system against viral infection through the mitochondrial antiviral signaling protein (MAVS)." (PMID 32033216, 2020). "MAVS depletion disrupts pro-inflammatory and anti-virus cytokines production that is promoted by virus infection, so MAVS has an indispensable role in innate anti-virus immunity." (PMID 32316442, 2020). "During viral infection, TRIM31 is recruited to mitochondria, where it catalyzes K63-linked polyubiquitination of MAVS at lysine residues 10, 311, and 461 to facilitate the formation of prion-like aggregates." (PMID 32117959, 2020). "Because MAVS is essential for virus infection-induced signaling and interacts with RNF115, we next investigated the role of RNF115 in RNA virus-triggered signaling." (PMID 33139700, 2020). "Mitochondrial antiviral signaling protein (MAVS), a signaling adaptor with antiviral feature in the mitochondrial membrane, is critical for host defenses against viral infection." (PMID 32190169, 2020). "The capsid protein VP16 of herpes simplex virus 1 blocks the production of early ISGs mediated by peroxisome MAVS, inhibiting the early peroxisome-mediated response to viral infection." (PMID 32536927, 2020). "During viral infection, mitochondrial antiviral signaling protein (MAVS) nucleates the formation of a signaling complex upon RIG-like Receptor (RLR) stimulation that is required for induction of Type I interferon." (PMID 33520735, 2020). "NS3/4A cleaves MAVS at Cys508, which dislodges the N-terminal fragment of MAVS from the mitochondria, reduces downstream signaling, and enables persistent viral infection." (PMID 32536927, 2020). "For example, upon viral infection, TRIM14 undergoes K63-linked polyubiquitination, which provides a platform for the binding of IKKγ/NEMO to MAVS on OMM." (PMID 32117959, 2020). "For example, K48-linked ubiquitination of MAVS mediated by the E3 ubiquitin ligase AIP4 (also known as Itch) is promoted by the poly (C)-binding protein 2 (PCBP2), which is upregulated after viral infection." (PMID 32536927, 2020). "Further work in this area is expected to provide a clearer understanding of MAVS activity in antiviral immunity and to fuel the discovery of new drugs for the treatment of viral infection." (PMID 32536927, 2020). "Our results showed that the protein level of MAVS increased at the earlier times (9 and 12 h), and then decreased at the latter times (24, 36, 48 h) post virus infection or poly I:C." (PMID 32943610, 2020). "During viral infection, activated caspase-3 cleaves MAVS at Asp429 and Asp490 and inhibits excessive signaling." (PMID 32536927, 2020). "In this regard, yeast two-hybrid screens identify poly rC binding protein 1 (PCBP1) and PCBP2 as positive regulators of the interaction between ITCH/AIP4 and MAVS, whose levels are increased upon viral infection." (PMID 32117959, 2020). "Taken together, these results suggested that RNF115 constitutively interacts with MAVS and viral infection leads to their disassociation." (PMID 33139700, 2020). "Additional negative regulatory mechanisms in MAVS-mediated antiviral immunity include phosphorylation of MAVS by Nemo-like kinase, which occurs in the later stage of viral infection and induces MAVS degradation." (PMID 32536927, 2020). "GPATCH3 binding to MAVS prevents the assembly of the MAVS/TRAF6/TBK1 complex during viral infection." (PMID 32536927, 2020). "MAVS dependent pathway at the mitochondria act as a critical factor for limiting virus infection and a detailed understanding of its regulation can help fine tune the host immune responses toward a productive antiviral strategy." (PMID 32983015, 2020).
viral infection (continued). "Protein phosphorylation is a second main type of PTM that controls MAVS signaling during viral infection." (PMID 32117959, 2020). "TAX1BP1 regulates MAVS degradation under physiological conditions and during viral infection in a similar manner to PCBP1/2." (PMID 32536927, 2020). "This discrepancy strongly indicated that virus infection warranted CORT-induced degradation of MAVS via Mfn2 upregulation." (PMID 32943610, 2020). "We identified an unexpected decreased in the transcription of OGT in response to virus infection; this resulted in the global reduction of cellular O-GlcNAcylation and the specific reduction of the O-GlcNAcylation of MAVS." (PMID 33603735, 2020). "During the later stages of viral infection, MAVS activity is negatively regulated by UBX-domain-containing protein 1 (UBXN1), a member of the ubiquitin-binding protein family." (PMID 32536927, 2020). "Ubiquitination is a reversible process, and viral infection also upregulates the expression of ovarian tumor family deubiquitinase 4 (OTUD4), which removes K48-linked ubiquitin from MAVS and thus reduces its degradation." (PMID 32536927, 2020). "Although most endogenous NLK was located in the nucleus, NLK in the cytosol colocalized very well with MAVS, and this colocalization was especially enhanced in MAVS prion-like aggregates after virus infection." (PMID 31324787, 2019). "zbTRIM25 promotes K63 polyubiquitination of both zbRIG-I 2CARD and RD regions, which subsequently induces the activation of downstream signaling event via MAVS and thereby inhibits viral infection." (PMID 31849979, 2019). "Our study highlights that MAVS expressed by CD11c+ DCs restrains viral replication, B cell activation and humoral responses during virus infection." (PMID 31242236, 2019). "Here, we show that NLK inhibits the antiviral immune response during viral infection by targeting MAVS for degradation." (PMID 31324787, 2019). "As reorganization of MAVS spatial distribution is a key event in IFN production in response to viral infection, such spatial reorganization has important consequences." (PMID 31322806, 2019). "Virus infection can reportedly promote the oligomerization of MAVS into a large prion-like signaling structure." (PMID 31324787, 2019). "It has also been observed that preceding viral infection, the human mitochondrial protein (MAVS) forms functional prion-like polymers for activating a highly sensitive and robust mechanism of the immune response." (PMID 31277491, 2019). "MAVS recruits TRAF3 to ASC in the context of viral infection, which ubiquitinates ASC promoting its oligomerization, and it therefore enhances NLRP3 inflammasome activation." (PMID 31284572, 2019). "Here, the use of a simple single-step WCE preparation coupled to SDD-AGE preserved the detection of MAVS high MW aggregates induced in response to RIG-I sensing of virus infection." (PMID 29385716, 2018). "MAVS is known to function as a key adaptor that connects the RLR recognition of virus infection to innate immune responses, thereby limiting virus replication and dissemination in the host." (PMID 29746593, 2018). "These deubiquitinases can be activated during viral infection, and then stabilize MAVS, or TRAF3, or TRAF6 protein, which finally promotes IFNs production and host antiviral defense." (PMID 29734366, 2018). "Here, our findings uncover the phenomenon of MAVS/TRAF3/TRAF6 downregulation at the early stage of viral infection, and partially clarify the mechanisms of the dynamics of downregulation of the signalosome and IFNs induction." (PMID 29734366, 2018). "Overall, our study identifies cytosolic TRIM21 as a positive regulator of CVB3-triggered MAVS-mediated type I Interferon signaling pathway that restricts viral infection." (PMID 30410495, 2018).
viral infection (continued). "Recently, Xue et.al have reported that TRIM21 is upregulated upon RNA virus (SeV, VSV) infection, interacts with MAVS and catalyzes the K27-linked polyubiquitination of MAVS, thereby promoting the activation of IRF3 and inhibiting viral infection." (PMID 30410495, 2018). "It is well established that virus infections sensed by the RLRs pathway trigger MAVS aggregation and activation." (PMID 29385716, 2018). "MAVS mediates activation of nuclear factor kappa B (NF-κB) and interferon regulatory factors (IRFs) and the induction of interferons in response to viral infection." (PMID 30326919, 2018). "On the other hand, direct association of NLRX1 with MAVS and STING inhibits MAVS-RLR pathway and STING-TBK1 signaling, respectively, thereby suppresses type I IFN response and promotes viral infection." (PMID 30559741, 2018). "Mechanistically, the interaction between TRIM31 and MAVS catalyzes the Lys63 (K63)-linked polyubiquitination of Lys10, Lys311, and Lys461 on MAVS, which forms prion-like aggregates of MAVS in response to viral infection." (PMID 30072974, 2018). "We cannot rule out the possibility that mitochondrial elimination impairs MAVS-dependent anti-viral immunity and promotes virus infection as well." (PMID 29772718, 2018). "But the mechanisms of MAVS activation are different under overexpression or viral infection/polyI:C stimulation conditions." (PMID 29988497, 2018). "Upon viral infection, TRIM14 undergoes Lys-63-linked polyubiquitination at lys-365 and recruits NF-κB essential modulator to the MAVS signalosome, leading to the activation of both IRF3 and NF-κB pathways." (PMID 28211536, 2017). "As expected, PYR-41 treatment inhibited MAVS aggregation in HEK293T cells on virus infection, indicating that a ubiquitination event is indeed critical for RIG-I to activate MAVS following virus infection." (PMID 28469175, 2017). "Although monomeric MAVS recombinant protein can assemble into prion-like filaments spontaneously in vitro, endogenous MAVS in cells is prevented from aggregation until viral infection." (PMID 28607490, 2017). "Upon viral infection, peroxisomal MAVS (MAVS-Pex) triggers an immediate early induction of ISGs, which is type I IFN-independent, whereas mitochondrial MAVS shows a delayed and sustained antiviral effect based on the induction of type I IFNs and ISGs." (PMID 28222744, 2017). "After viral infection, MAVS is regulated negatively or positively by different mechanisms, including mitochondrial dynamics, post-translational modifications, or protein-protein interactions." (PMID 28542569, 2017). "Recent studies have revealed that STING acts as a scaffold protein for TBK-1 and IRF3 and links them to the MAVS complex in mitochondria upon viral infection." (PMID 29201911, 2017). "Consistently, type I IFN production correlated with MAVS aggregation in these knockout cell lines on virus infection." (PMID 28469175, 2017). "After MAVS activation during viral infection, IRF3/NF-κB is stimulated to induce IFN, whereas TAK1/MAPK is also activated to modulate cell proliferation." (PMID 28394926, 2017). "Deletion of MAVS reduces innate immune responses to viral infection, which results in increased virus replication." (PMID 28953980, 2017). "During viral infection, 5′ppp RNA PAMPs bind to R-terminal region of RIG-I, which cause the release of CARD to trigger CARD-depended interaction with mitochondrial antiviral signaling protein (MAVS) that is located on the outer mitochondrial membrane." (PMID 29163506, 2017). "Although it has been well studied how RLRs recruit and activate MAVS upon virus infection, it remains to be elucidated how MAVS activates its downstream components, including kinases TBK1/IKKε and the IKK complex." (PMID 29125880, 2017). "They further demonstrate that during viral infection, MAVS recruits TRAF6 that subsequently directly binds with GP73." (PMID 28394926, 2017).